IL1RN (interleukin 1 receptor antagonist)
Diseases named in the same sentence as IL1RN in open-access papers (continued):
Sharing a sentence is not in itself a finding about the gene and the disease.
tendinitis (1 paper, 2025). Inflammation of a tendon, usually resulting from an overuse injury. "Collectively, these transcriptomic findings suggest that SM102 LNPs-Il1rn mRNA exerts dual therapeutic effects in tendinitis by targeting IL-1 signaling—simultaneously inhibiting inflammatory cascades and activating collagen-driven ECM restoration." (PMID 40873435, 2025).
type 1 diabetes (1 paper, 2015). "In an in-vivo study, patients with type 1 diabetes carrying IL-1RN*1/*1 genotype had 30 % lower levels of plasma IL-1Ra compared with levels in patients carrying the IL1RN*1/*2 genotype further suggesting an enhancing effect of IL1RN*2 allele on IL-1Ra circulating levels in healthy carriers." (PMID 27030821, 2015).
urolithiasis (1 paper, 2023). Stone(s) within the urinary tract. "However, previous reports have focused on the frequency of polymorphisms located in IL-1RN, IL-1β, and IL-18 genes in patients with urolithiasis." (PMID 37878647, 2023).
vasculitis (1 paper, 2019). "Thus, IL-1A, IL-1B, and IL1RN are considered attractive candidate genes for vasculitis." (PMID 31093510, 2019).
tumor (71 papers, 2009 to 2026). "In PDAC, the IL‐1 family has been implicated in altering the tumor immune microenvironment, with higher tumor expression of IL1RN associated with poorer survival." (PMID 39660530, 2024). "We compared the tumor growth in immune-competent and immune-deficient mice and found that the disruption of Il1rn gene resulted in severe suppression in the former." (PMID 37563620, 2023). "IL1B is a pro-inflammatory cytokine that has been shown to be associated with tumor growth and metastasis, while IL1RN is a receptor antagonist for IL1." (PMID 34771668, 2021). "Tumor purity was significantly positively associated with IL1RN methylation (R = 0.447, P = 7.49e-32)." (PMID 33238942, 2020). "Our work further demonstrated that high IL1RN expression was significantly associated with decreased tumor purity and increased immune infiltration." (PMID 33238942, 2020). "Upregulation of IL1RN has been demonstrated in various tumor types in association with increased cell proliferation and a higher risk of metastasis." (PMID 30602372, 2019). "Tumor associated macrophages were enriched in M2 genes, Arg1, Il1rn, and Tgfb1." (PMID 35600339, 2022). "It is possible that that the initial immune-activation function of increased inflammation after IL1RN reduction does cause tumor cell death in the elimination phase, but it also accelerates the process of selection for resistance to immune surveillance functions." (PMID 32244522, 2020). "Our hypothesis that GBC-PC might present similar immunosuppressive properties as TAMs, which are implicated in inhibitory anti-tumor responses, is supported by the clear upregulation of Il4ra and Il1rn gene expression in GBC-PC." (PMID 28978142, 2017). "IL1RN, here down-regulated by arsenic exposure, is known to inhibit the activity of IL-1, a major human cytokine implicated in inflammatory responses that contribute to tumor development." (PMID 21457566, 2011). "Tumor-infiltrating lymphocytes (TILs) in the tumor microenvironment release a naturally occurring anti-inflammatory substance called interleukin-1 receptor antagonist (IL1RN)." (PMID 39125732, 2024). "Concerning the clinical studies available in databases, all genes in this study, except for IL1RN, which is more expressed in tumor tissue, showed higher expression levels in normal than in tumor tissue." (PMID 39201290, 2024). "The exact mechanism linking methionine with reduced IL1RN expression and its biological effect on the tumour is unclear." (PMID 39595047, 2024). "As a result, tumor cells attract TILs through pro-inflammatory chemokines, leading to the creation of an anti-inflammatory environment mediated by IL1RN in the syngeneic prostate cancer model." (PMID 39125732, 2024). "Consistently, we found an increase in CD8+ T cells and a decrease in CD11b+Ly6G− immunosuppressive mononuclear population in the tumor microenvironment of Il1rn KO-derived tumors." (PMID 37563620, 2023). "The epithelial activation markers REG and SERPINA5, the interferon response marker MX1, and the anti-inflammatory protein IL1RN were found significantly deregulated in tumour tissue, similar to the inflamed tissue." (PMID 36961872, 2023). "The anti-tumor effect of Il1rn KO has promoted us to monitor the immune profile of T cells and myeloid (CD11b+) populations in the TME." (PMID 37563620, 2023). "We found that the Il1rn KO cells exhibited greater tumor inhibition in immune-competent mice, highlighting the crucial role of a functional immune system in Il1rn KO-mediated anti-tumor response." (PMID 37563620, 2023). "Statistical analysis confirmed a significantly stronger anti-tumor effect of Il1rn KO in immune-competent mice than in ASID mice." (PMID 37563620, 2023). "For instance, the pro‐inflammatory gene markers IL1A/B were overexpressed in the peri‐tumor tissue, whereas IL1RN was significantly upregulated in the tumor core, which is an inhibitor of IL1A/B." (PMID 37434432, 2023).
tumor (continued). "Existing literature suggests that IL1RN is closely related to tumor immunity and tumor metabolism, of which further studies are needed to investigate its value in the prognosis of immune infiltration." (PMID 36483329, 2022). "Both assays thereby indicate an inverse correlation between IL1RN expression and tumor cell invasive capacity and migration." (PMID 34070905, 2021). "We found that tumor-infiltrating leukocytes are crucial for establishing a tumor type-specific anti-inflammatory microenvironment partly through secretion of IL1RN." (PMID 32244522, 2020). "Although the pro-inflammatory chemokine Ccl2 was highly activated in the LLC-derived tumor, we found that the Il1rn level was increased in LLC-derived tumor tissue (~four-fold) and its corresponding TILs (~50-fold) when they were compared to LLC cell line." (PMID 32244522, 2020). "We also analyzed the mRNA levels of IL1RN in different tumor stages from a published clinical dataset." (PMID 32244522, 2020). "When monitoring the mRNA level of Il1rn, tumor tissues collected from mice showed increased levels compared with the derived primary cells in vitro (2–6 fold)." (PMID 32244522, 2020). "We demonstrate that tumor-infiltrating leukocytes (TILs) secreted IL1RN in TRAMP-C1-derived tumor microenvironment and that IL1RN can inhibit the functions of pro-inflammatory cytokines in vitro." (PMID 32244522, 2020). "IL1RN expression positively correlated with immune infiltration, tumor progression and poor OS for all cancers." (PMID 33238942, 2020). "Of note, tumor Tregs highly expressed IL1RL1 and IL1RN, which have been associated to inhibition of IL-1-mediated inflammation." (PMID 32601304, 2020). "Several studies have shown that IL1RN can act as an anti-tumor agent partly through inhibiting the IL1 signaling." (PMID 32244522, 2020). "In the tumor microenvironment, the TILs secrete a natural anti-inflammatory factor, interleukin-1 receptor antagonist (IL1RN), which inhibits the functions of pro-inflammatory molecules and likely accounts for tumor type-specific anti-inflammation functions." (PMID 32244522, 2020). "In summary, our results support a working model that tumor cells can recruit TILs through tumor-derived chemokines, and TILs suppress inflammation in the local environment via IL1RN-mediated functions." (PMID 32244522, 2020). "In summary, we demonstrated that the IL1RN served as a tumor-type-specific anti-inflammatory cytokine in the TRAMP-C1-derived TME." (PMID 33322099, 2020). "Further investigations are warranted to understand the role of IL1RN-secreting TILs in tumor biology." (PMID 33322099, 2020). "Higher IL1RN expression was significantly associated with shorter progression-free survival (PFS), advanced tumor stage, tumor metastasis, increased incidence of BRAF mutations, and decreased incidence of N-RAS and H-RAS mutations." (PMID 33238942, 2020). "Consistent with the roles of inflammation in tumor promotion, the IL1RN was reported to be an antitumor agent partly through inhibiting IL1R1 signaling." (PMID 33322099, 2020). "IL1A and IL1B were found to be significantly increased in tumors (b p < 0.0001 and p = 0.003, respectively) compared to normal samples while IL1RN (IL-1RA) was significantly decreased in tumor versus normal tumors (p = 0.02)." (PMID 31346466, 2019). "Our PCR array data showed that both M1-related genes (Ccl2, Ccl3, Ccl4, Ccl5, Il12b, Il1b and Ccl1) and M2-related genes (Il10, Tgfb2 and Il1rn) were significantly upregulated in NM11-shsST2 tumours compared with NM11-shCont tumours." (PMID 27882929, 2016). "We found an inverse correlation between tissue protein levels of IL1RN and more advanced tumor stages." (PMID 25114677, 2014). "These included genes known to be expressed by microglia (CCL8, SPP1, IRF7, IL1RAP), macrophages (IL1RN, SPP1, PDPN, IL1RAP, MDK, TFRC, HRH4), and tumor-associated macrophages (IL6, SPP1)." (PMID 22937035, 2012).
tumor (continued). "Similarly, compared to CAF‐S4, CAF‐S5 also upregulates CCL4, CXCL9, CXCL10, CXCL11 and IL1RN suggesting that cytokine and chemokine transcripts are enriched in tumours with high CAF‐S1 and CAF‐S5 and low in the myCAF‐like subset CAF‐S4." (PMID 39743376, 2025). "IL-1β and IL1RN can promote tumor angiogenesis and the recruitment of immune suppressor cells." (PMID 39684426, 2024). "Notably, the proportion of neutrophils increased in the metastatic samples, transcriptionally resembling tumor-associated neutrophils (TAN), with a high expression of VEGFA, LGALS3, OLR1, PROK2, MMP9, and IL1RN." (PMID 38358826, 2024). "Since IL-1β has been shown to exhibit both pro-tumor and anti-tumor effects, we examined whether the proliferation activities in response to IL-1β were influenced by Il1rn KO." (PMID 37563620, 2023). "Based on these results, it would be interesting to know whether delivering IL1RN KO MSCs also enhances anti-tumor effects." (PMID 36672395, 2023). "Notably, several genes related to matrix composition and immune cell recruitment were upregulated in squamous cells (Anxa1, Ecm1, Il1rn, Itgb4), as well as genes that are reported to be tumor suppressors (Serpin5b, Phlda3)." (PMID 35600339, 2022). "Our study also showed a significant correlation between IL1RN expression and various cytokines, which implied that IL1RN may play a complex role in tumor immunity." (PMID 33238942, 2020). "The complex interactions with T cells and other types of cells, as detected in our enriched TILs, may play an important role for IL1RN expression in the tumor microenvironment." (PMID 32244522, 2020). "Further investigation is warranted to understand the role of IL1RN in tumor biology." (PMID 32244522, 2020). "Consistent with our findings, previous studies have focused on the role of IL1RN in tumor immunity." (PMID 33238942, 2020). "The negative association between IL1RN and tumor progression in the earlier study recapitulates molecular features of the immunoediting theory, which consists of three major phases of elimination, equilibrium, and escape." (PMID 32244522, 2020). "Because IL-1 is critical for tumor immunity, elevation of IL1RN expression may result in a general environment favourable to tumor cells and enhance the metastatic and recurrence potential of tumors by changing local IL-1-dependent pathways." (PMID 33238942, 2020). "Additionally, pro-inflammatory markers (e.g., IL1α and IL1β) were highly expressed at the tumour periphery, while a more anti-inflammatory phenotype (e.g., IL1RN) was observed in the tumour core." (PMID 31973030, 2020). "At this stage, PTEN-null lesions showed a concomitant presence of both senescent and proliferative cells; however, the massive infiltration of MDSCs induced secretion of interleukin-1 receptor antagonist (IL-1RA), which hampered the senescence response, thus sustaining tumor growth." (PMID 31658667, 2019). "Whether a low expression of IL1RN is an early driver of UCB carcinogenesis or a later consequence of complex alterations in advanced tumor stages remains to be clarified in further investigations." (PMID 25114677, 2014). "IL1RN, MAL and MMP1 are prospective tumor diagnostic markers for HNSCC." (PMID 19835631, 2009). "IL1RN has also been shown to be involved in tumorigenesis in numerous tumor entities." (PMID 19750229, 2009). "Therefore, IL1RN methylation modulation in these monocyte subsets may influence their cytokine output within the tumor microenvironment." (PMID 40668918, 2025). "IL1R1 and IL1RN expression varied widely in different tumors, suggesting that ligand-receptor-antagonist regulation may possess different equilibrium points in different tumor environments." (PMID 40535567, 2025). "This suggests that IL1RN editing may drive macrophages toward an inflammatory transcriptional program associated with ISG and IL1B monocyte identities, which is further amplified in the tumor context." (PMID 40668918, 2025).
tumor (continued). "Using GO and KEGG functional enrichment analyses, we found that hub genes are involved in tumor immunity in their functions, so we performed an immunobioinformatics database search of 15 key genes to identify potential immune infiltration marker roles of IL1RN and PRRX1." (PMID 36483329, 2022). "However, emerging evidence also supports a tumor-promoting role of the IL1RN." (PMID 33322099, 2020). "Since tumor cells death due to androgen deprivation already imposes strong inflammation stress in the tumor microenvironment, increased IL1RN may be a natural host response to ameliorate the collateral tissue damages, which also serves to delay the malignant progression." (PMID 32244522, 2020). "However, IL1RN secretion by TILs during ADT might provide a TME favoring CRPC development at certain tumor stages." (PMID 33322099, 2020). "However, we are aware that IL1RN and its related TILs may also serve as tumor-promoting agents facilitating tumor progression in certain conditions." (PMID 32244522, 2020). "Therefore, the results suggested that the IL1RN secreted by TILs/CD11b− may be involved in protecting both host tissues and tumor cells from inflammation-induced cytotoxic effects." (PMID 33322099, 2020). "In addition, they had increased expression of the inhibitor interleukin 1 receptor antagonist (Il1rn) and of the FK506 Binding Protein 5 (Fkbp5); the latter was shown to play a key role in the immune suppressive activity of tumor associated suppressor granulocytes." (PMID 28620383, 2017). "Several proteins, including S100A7, IL1RN, and CXCL8, were identified as potential biomarkers for HPV-positive tumours." (PMID 41487403, 2026). "Among these genes, IL1RN and IL36G function as key regulators whose silencing inhibits M2 polarization and attenuates tumor proliferation, invasion, migration, and epithelial-mesenchymal transition." (PMID 41704537, 2026). "The genes encoding the most consistently differentially secreted cytokines, including IL-1RN, IL-1β, and IP10, are highly expressed in ISG and IL1B monocytes and up-regulated in the tumor microenvironment." (PMID 40668918, 2025). "Specifically, cytokines involved in tumor progression such as CXCL8, EBI3, and IL1RN were upregulated in the triculture samples compared to other conditions." (PMID 40056038, 2025). "Comparative analysis revealed tumor-specific upregulation of GLRX3, IL1RN, and TNFRSF4 (p < 0.001), contrasting with downregulation of FCGRT, UBN2, and WNT5B in EC versus normal tissues." (PMID 40722666, 2025). "Lastly, TAM5, enriched in the primary tumor (PT), exhibited high expression of various immunosuppressive factors, including IL1A, IL1B, IL1RN, and IL6." (PMID 39236316, 2024). "Ligands of IL1 receptor inhibitor with receptors of IL1RN and IL1B shared similar roles in immune escape and tumor metastasis." (PMID 38944814, 2024). "To explore the biological function of tumor cell-derived IL-1Ra, we conducted an orthotopic injection procedure with immune-competent C57BL/6JNarl mice (designated B6), using the Ctrl and Il1rn KO clones." (PMID 37563620, 2023). "Other highly upregulated genes with tumor suppressor and/or cell cycle inhibitory activities are laminin-5 (LAMB3, LAMC2) and IL1RN, which were increased by 10- to 15-fold." (PMID 34349241, 2022). "Other highly upregulated genes with tumor suppressor and/or cell cycle inhibitory activities are LAMB3, LAMC2, and IL1RN, which were increased by 10- to 15-fold." (PMID 34349241, 2022). "Some M1 markers (IL1A, IL1B, CD86), M2 markers (CCL18, MRC1/CD206, CSF1R), and TAM markers (HLA-DR, IL1RN, CD163, ITGAM, SIGLEC1/CD169) were highly expressed on both tumor and non-tumor macrophages." (PMID 33918618, 2021). "Remarkably, we have also found that the expression of PD-L1, which has an immunosupressive function in the anti-tumor immune reaction, correlated inversely with EMT transcription factors related to barriers (CDH2, CAV2, DSC2, and IL1RN)." (PMID 34527572, 2021).